RHOA (ras homolog family member A)
Diseases named in the same sentence as RHOA in open-access papers (continued):
Sharing a sentence is not in itself a finding about the gene and the disease.
tumor (continued). "In addition, PD‐L2 can also induce autophagy through beclin‐1, as another upstream signal of the RhoA‐ROCK‐LIMK2 signaling pathway, beclin‐1 can also control cellular autophagy by regulating RhoA‐ROCK‐LIMK2 signaling pathway and also influence the tumor metastasis." (PMID 38800967, 2024). "Indeed, among the most upregulated genes in FAT4 knockdown cells we found ARHGEF6, encoding for the guanine nucleotide exchange factor αPIX that activates Rac1 and Cdc42 GTPases and ARHGDIB, a negative modulator of the RhoA tumor suppressor." (PMID 39478125, 2024). "In BCPAP cells treated for 72 h, genes from the canonical Wnt pathway (FZD1, DVL1, AKT2, CTNNB1, LEF1, MYC) and the non-canonical Wnt pathway (RHOA, related to cytoskeletal dynamics and increased migration and invasion) were upregulated, suggesting pro-tumor behavior." (PMID 39125748, 2024). "However, mutations in RhoA are not frequent and accumulating evidence supports a role for its regulators including ARHGEF2 as well as the effectors ROCK1/2 and MLCK in tumor development and progression." (PMID 38970683, 2024). "The RhoA and PI3K-Akt pathways, which are common signal transduction pathways, play important roles in the development and progression of cancer, especially in the regulation of TGFβ induced epithelial mesenchymal transition (EMT), tumor progression and angiogenesis." (PMID 38053093, 2023). "In addition, the expression of RHOA in different tumor stages had different degrees of expression than that in normal tissues, but the difference was not significant." (PMID 36882618, 2023). "Because RHOA is involved in both T-cell receptor downstream signalling and cell migration, we hypothesized that the characteristic presentation of AITL could be the result of enhanced tumor cell migration." (PMID 37370838, 2023). "Therefore, we believe that RhoA is a downstream regulator of LEMD1, and LEMD1 could affect cytoskeleton changes and tumor cell migration in part through the RhoA/ROCK1 signaling pathway." (PMID 35619906, 2022). "Moreover, RHOA activity can also be inhibited by Snail to recruit SRC-phosphorylated p190 RHOGAP, thereby promoting collective migration and the formation of circulating tumor cell clusters." (PMID 36348464, 2022). "Indeed circ-IARS induced significant downregulation of miR-122 and ZO-1 expression, while it upregulated RhoA and RhoA-GTP levels, increased F-actin expression, focal adhesion formation, and enhanced endothelial permeability; thus, promoting tumor invasion and metastasis." (PMID 35454874, 2022). "Tumour cells from mice injected with siHNRNPC‐silenced PanC‐1/NF co‐cultures had significantly decreased HNRNPC, RhoA, ROCK2 and YAP expression, suggesting that radiation resistance is mediated via HNRNPC and the downstream RhoA/ROCK2/YAP signalling pathway in PC." (PMID 35277915, 2022). "The tumor-promoting effect of circ-NOLC1 was inhibited by knockdown of ESRP1, CDK1, or RhoA expression in circ-NOLC1-overexpressing cells, which might act by modulating RhoA and CDK1 expression." (PMID 33483472, 2021). "Thus, we investigated the expression of the tumor markers c-MET, RhoA, and CLDN18 by immunohistochemistry (IHC) in a large and extensively characterized Western cohort of resected GC and its correlation with clinicopathological characteristics and survival outcomes." (PMID 35076580, 2021). "Two recent studies have suggested that tumour cells may adapt to FSS and biomechanical constriction forces by activation of the RhoA-ROCK pathway, a key regulator of cell cytoskeleton in eukaryotic cells involving the signalling protein GTPase RhoA." (PMID 34241735, 2021). "Tumour-derived exosomes also increase permeability of endothelial monolayer cells via transferring circ-IARS into recipient cells and activating their miR122/RhoA signalling, thereby leading to upregulation of F-actin and downregulation of ZO-1 and facilitating tumour metastasis." (PMID 34671031, 2021).
tumor (continued). "Interestingly, this study also found no change in the expression levels of RhoA between tumor and normal tissues, which contradicts earlier studies showing differences in RhoA." (PMID 32992837, 2020). "Altogether, we concluded that RhoA-activated SF cytoskeleton enables tumor cells to assemble periFN matrices and suppressing such periFN assembly with shFN non-autonomously promote fibroblast-mediated tumor growth." (PMID 33158289, 2020). "Here, we demonstrated for the first time that in vivo tumor growth could be reduced when the TMEs were devoid of CAFs which could be recruited and activated when RhoA/SF-aligned periFN was absent on tumor cell surfaces." (PMID 33158289, 2020). "Importantly, both WT-DLC1 and K714E-DLC1 were able to restore tumor growth from DLC1-KD A375 cells to a greater extent without altering RHOA activity, further confirming the oncogenic role of nuclear DLC1 independent of RhoGAP." (PMID 32214200, 2020). "However, previous reports indicated that RhoA was correlated with OS, DFS, T category (the extent of the primary tumor), TNM stage (international cancer classification system defined by UICC (Union for International Cancer Control)) and tumor differentiation." (PMID 31976530, 2020). "However, the level of expressional change in the stroma was much lower than that in the tumor, and the mouse expression profiles did not reveal any difference between RHOA mutants and mock/WT tumors." (PMID 31485674, 2019). "We speculated that the difference in the amount of small tumor nests was related to a difference in tumor-stromal interaction, and because the hypoxia signature was enriched in mock/WT but not in RHOA mutants, we focused on tumor angiogenesis." (PMID 31485674, 2019). "SV-LEC co-culture with tumor-educated macrophages led to a reduction in Tau of the biosensor from 1.797 ns ± 0.0252 ns to 1.622 ns ± 0.0338 ns, indicating an increase in FRET between the GFP- and RFP-terminal fluorophores and, consequently, an increase in RhoA activity." (PMID 31091437, 2019). "Together, this suggests that the effect of RhoA on tumor cell proliferation could be independent of its downstream effectors ROCK1 and ROCK2." (PMID 29535813, 2018). "Furthermore, ROCK, the effector of the RhoA GTPase, also plays a key role in tissue homeostasis through controlling mechanoreciprocity, including in the skin, and increased ROCK signalling and stromal stiffness are hallmarks of tumour progression." (PMID 28820907, 2017). "Additionally, FAK/RhoA signaling can act as downstream effectors of EphA2 for promoting tumor progression in non-metastatic RCC cells." (PMID 26177500, 2015). "A limitation of our mouse model in this study is that RhoA is deleted at the same time as K-RasG12D is expressed, and thus our work does not address whether RhoA plays a role in tumor maintenance or progression." (PMID 26030593, 2015). "Mechanistically, TP-mediated RhoA activation plays a critical role in the TXA2-induced tumour cell migration and metastasis while its ability to regulate the PI3′K and ERK cascades may account for the influence of TXA2 on tumour cell proliferation/mitogenesis." (PMID 26296974, 2015).
tumor (continued). "Due to c-Myc/RhoA pathway being conducive to tumor cell invasion and migration, we first investigate whether PIWIL2 modulates the invasion and migration features of tumor cells by performing Transwell and wound healing assays." (PMID 25193865, 2014). "In pre-decitabine tumor samples, expression of CTR1 and RhoA was lower and LINE-1 methylation tended to be higher in patients who were ≤3 months versus >3 months beyond most recent prior therapy, and LINE-1 methylation correlated inversely with expression of CTR1 and RhoA." (PMID 25024751, 2014). "It is tempting to speculate that by altering RhoA signaling, e.g. through activation of extracellular pathways, the tumor microenvironment might determine whether or not Activin B promotes invasion of ccRCC cells." (PMID 25343250, 2014). "Intriguingly, RhoA and RhoB reactivity was found to significantly increase with the proliferation index and grading of the tumours, but the authors did not correlate Rho GTPase expression with clinicopathological parameters, such as nodal status or patient survival." (PMID 23420497, 2013). "The atypical Rho protein Rnd3/Rho8/RhoE is an important regulator of migration of fibroblasts and tumor cells that acts by inhibiting RhoA through stimulation of the Rho GTPase-activating protein p190RhoGAP, and/or inhibition of the activity of ROCKI, one of the main effectors of RhoA." (PMID 21435554, 2011). "Furthermore, the expression level of RhoA was not related to the hormone (i.e. oestrogen and progesteron) status of the tumours (data not shown)." (PMID 12237774, 2002). "The same is true for RhoA expression and hormone status of the tumours (data not shown)." (PMID 12237774, 2002). "Given that IKK activation enhances Plexin-B1-dependent activation of RhoA, which is known to subsequently increase the promigratory activity of cancer cells and to increase tumour progression, the IKK-complex may exert some of its tumour-promoting activity through enhanced plexin signalling." (PMID 25137062, 2014). "Noncanonical pathways involves Wnt/β-catenin, PI3K/Akt, RhoA/ROCK1, MAPK/p38 or MAPK/ERK1/2 that mediate different effect of TGF-β on different tumor cells." (PMID 36614238, 2023). "Noncanonical pathways include RhoA/ROCK1, PI3K/Akt, Wnt/β-catenin, MAPK/p38, or MAPK ERK1/2, all of which mediate different effects of TGF-β on tumor cells." (PMID 34548615, 2021). "Noncanonical pathways include RhoA/ROCK1, PI3K/Akt, Wnt/β-catenin, MAPK/p38 or MAPK ERK1/2, which mediate different effects of TGF-β on tumor cells." (PMID 34548615, 2021). "In addition, the tumor-promoting effect of circ-NOLC1 was reduced after ESRP1, CDK1, or RhoA knockdown in circ-NOLC1-overexpressing cells, thus we hypothesized that circ-NOLC1 might function as an oncogene through binding and modulating ESRP1, CDK1, and RhoA levels." (PMID 33483472, 2021). "Statistically, the expression of RhoA did not correlate with other patient features, such as local progression (FIGO stage), tumor size (>4 cm or ≤4 cm), lymph node category or expression of other Rho-related proteins." (PMID 31976530, 2020). "These experiments together indicate that coincidental TGFß and AP-1 signaling are required for Arhgef17, RhoA, and MRTF activation that leads to non-canonical Hh signaling and tumor resistance." (PMID 33033234, 2020). "PD-L2 knockdown was found to attenuate the migration and invasion of OS cells via the inhibition of RhoA-ROCK-LIMK2 signaling in vitro, which could be another role of PD-L2 in tumor cells rather than in immune cells." (PMID 38730580, 2024). "We presented here that Rac1 activity but not RhoA or Cdc42 was increased significantly by PA treatment through CD36-Src-Akt signaling pathway, suggesting that Rac1 participated in triggering actin-remodeling and promoting LUAD tumor metastasis." (PMID 37612265, 2023).
tumor (continued). "Since RhoA knockdown had no observable effect on tumor angiogenesis, it is possible that the increased CXCL12 expression might drive the paracrine stimulation of the RhoA knockdown cancer cells’ invasiveness." (PMID 31705019, 2019). "Notably, PCAF promoted, whereas AARS1 did not affect, RHOA lactylation, highlighting the substrate-dependent regulation of lactylation; HDAC3 acts as a metabolic checkpoint, dynamically balancing lactylation levels to modulate RHOA signaling in tumor microenvironments." (PMID 41291745, 2025).
cancer (688 papers, 2003 to 2026). A tumor composed of atypical neoplastic, often pleomorphic cells that invade other tissues. "The yeast-based platform integrating growth assays and high-dimensional morphological profiling used in this study were effective for characterizing the functional classes of cancer-associated RHOA mutations." (PMID 41002403, 2025). "TMEM16 activates different signaling pathways in several types of cancers, including those associated with RhoA-ROCK and Ras-Raf-MEK-ERK1/2." (PMID 40332387, 2025). "Evaluating the expression of protein markers, particularly Rho GTPases linked to carcinogenesis and various cancers, we have demonstrated that overexpression of RhoA and Rac1, members of the Rho GTPase family, is associated with cancer progression." (PMID 39887960, 2025). "The PCAF/HDAC3 axis links lactate metabolism to RHOA signaling, revealing lactylation as a metabolic alternative to genetic mutations in cancer progression." (PMID 41291745, 2025). "We became interested in ARHGAP29, a putative RhoA GAP that is upregulated in many migratory cancer types and has variants that cause cleft palate." (PMID 41200767, 2025). "We established a yeast-based system for systematic phenotypic analysis of cancer-associated RHOA mutations." (PMID 41002403, 2025). "Several recurrent point mutations in RHOA have been identified across human cancers, with functional consequences that differ by the mutation site and cancer type." (PMID 41002403, 2025). "Human cancer development and progression have been linked to the activation of RhoA, which is facilitated by GEFs such as LARG, resulting in its effect on invasion and migration." (PMID 41338458, 2025). "In cancer, interestingly, dominant negative mutations of RhoA have been found, but constitutively active or fast-cycling mutants have not been found." (PMID 40136653, 2025). "RHOA, a member of the Rho family of small GTPases, harbors recurrent mutations in diverse cancers, but how these mutations cause their cellular effects remains poorly understood." (PMID 41002403, 2025). "Signaling via MEK/ERK and AKT/PI3K are linked to RhoA kinase activity and vascular smooth muscle cell (vSMC) contractility in the periphery, but largely unexplored in the cancer vasculature." (PMID 40140727, 2025). "Activation of RhoA was reported to be related to the transformation of endothelial cells into cancer-associated fibroblasts through EndMT49." (PMID 38250154, 2024). "EphB2 receptors interact with EphrinB1 to regulate cell-to-cell adhesion, in which EphrinB1 causes dissociation and activation of RhoA through direct binding to RhoGDI1, thereby promoting cancer cell migration and invasion." (PMID 39768163, 2024). "HMCN1 markedly regulate cancer associated fibroblasts migration via the RhoA/ROCK signaling pathway." (PMID 39050894, 2024). "RhoA mutations appear restricted to certain cancer types and distinct RhoA mutational hotspots are associated with different cancer types." (PMID 38970683, 2024). "Loss of β4 expression in cancer cells seems to stimulate their invasiveness through the enhanced activation of the RhoA pathway, favoring amoeboid migration of the cells, and the amplitude of INaP." (PMID 37456756, 2023). "Ras homolog family member A (RhoA) participates in angiogenesis and proliferation in cancer, and the RhoA-rho-associated protein kinase (Rock) signaling cascade is involved in trophoblast migration." (PMID 36834865, 2023). "The role of β4 as a cancer suppressor protein in this cell line was associated to the overactivation of RhoA GTPase activity, and cytoskeletal reorganization promoted by the intracellular C-domain of the β4 subunit." (PMID 37456756, 2023). "Intriguingly, we demonstrated that several cancer-related mutations of RhoA also disrupt the TRPV4-RhoA binding interface." (PMID 37353484, 2023).